SLC26A4 (solute carrier family 26 member 4)
Diseases named in the same sentence as SLC26A4 in open-access papers (continued):
Sharing a sentence is not in itself a finding about the gene and the disease.
hearing loss (continued). "Consequently, the clinical finding of an EVA in the context of hearing loss does not unequivocally imply biallelic pathogenic sequence alterations in SLC26A4, providing a strong imperative for genetic testing to offer the correct diagnosis and the best possible patient care." (PMID 40121402, 2025). "However, it is still not clear whether mutations in SLC26A4 lead to hearing loss via regulation of the PI3K/Akt/mTOR pathway." (PMID 36072472, 2022). "Although previous studies have identified genetic factors such as mutations in SLC26A4 and GJB2 as contributors to age-related hearing loss, our study did not include genetic testing." (PMID 39834439, 2025). "Reverse dot blotting for 16 hotspot variants in the GJB2, GJB3, SLC26A4, and MTRNR1 genes was performed to rule out common variants in hereditary hearing loss." (PMID 30068307, 2018). "The role of SLC26A4 sequence alterations in determining PS and EVA was firmly established by several studies, either focusing on hearing impairment, alteration of the vestibular aqueduct, suppression of thyroid function or combinations of these clinical manifestations." (PMID 29320412, 2018). "Variations in SLC26A4 and GJB2 in 28 children with bilateral severe-to-profound non-syndromic hearing loss (NSHL) without familial history were analyzed using Sanger sequencing." (PMID 28383030, 2017). "Loss of function in both SLC26A4 and GJB2 have been implicated in syndromic and non-syndromic hearing loss." (PMID 28222800, 2017). "Genetic analysis of 115 variants in common genes related to HL, GJB2, SLC26A4 and MT-RNR, was performed on 695 subjects with non-syndromic hearing loss (NSHL) from the Northern China." (PMID 27792752, 2016). "Two questions were raised: can the autosomal recessive SLC26A4 mutations cause hearing impairment without EVA or other inner ear malformation, and are there other genes involved in the pathogenesis of hearing loss with SLC26A4 (digenic)." (PMID 19040761, 2008). "In hearing loss patients negative of GJB2, SLC26A4, and mitochondrial 12S rRNA, Usher and Waardenburg syndrome-related genes account for a major proportion in Chinese Han families, followed by STRC causing mild to moderate hearing loss." (PMID 36504663, 2022). "Although GJB2 and SLC26A4 mutations were absent in our patients, our results show that CDH23 mutation caused ARNSHL in 2 of 13 (15%) affected Korean families and that 3 of 93 patients with hearing loss carried a heterozygous mutation." (PMID 24767429, 2014).
Pendred syndrome (139 papers, 2004 to 2026). "Nonetheless, comprehensive genetic testing should be considered for patients with Pendred syndrome, and family-based screening is recommended once pathogenic SLC26A4 variants are identified." (PMID 41695370, 2026). "Pendred syndrome (PDS) is an autosomal recessive disease caused by variants in SLC26A4 manifesting thyroid dyshormonogenesis." (PMID 40956475, 2025). "While Pendred syndrome is invariably linked to biallelic pathogenic sequence alterations in the SLC26A4 gene, in Caucasian cohorts these are found only in approximately 25% of EVA patients." (PMID 40121402, 2025). "About 600 pathogenic SLC26A4 variants are known to cause either nonsyndromic recessive hearing loss (DFNB4) or Pendred syndrome (hearing loss and thyroid dysfunction)." (PMID 41226768, 2025). "Mutations in the SLC26A4 gene, such as those associated with Pendred syndrome and DFNB4, profoundly impact TM structure and function through both TH-dependent and TH-independent mechanisms." (PMID 40901670, 2025). "Pendred syndrome (PS) is an autosomal recessive disorder caused by mutations of the SLC26A4 gene and characterized by a combination of sensorineural deafness and goiter, with or without hypothyroidism." (PMID 41394090, 2025). "Pathogenic variants in SLC26A4 are a common cause of HL associated with EVA, causing either nonsyndromic HL, DFNB4, or Pendred syndrome (association of HL and goiter due to an iodine organification defect), which both have a recessive inheritance." (PMID 39383236, 2024). "SLC26A4 gene encodes the anion exchanger pendrin, of which the variants will lead to non‐syndromic recessive HL and Pendred syndrome." (PMID 38407562, 2024). "So far, various mutations of SLC26A4 have been reported in Iran, which include a wide range of phenotypes from “Pendred syndrome” to non-syndromic “Deafness, autosomal recessive 4, with enlarged vestibular aqueduct”." (PMID 39465527, 2024). "Mutations in SLC26A4 occasionally cause Pendred syndrome, a syndromic hearing loss accompanied by goiter and hypothyroidism." (PMID 39609929, 2024). "Both DFNB4 and Pendred syndrome are inherited as autosomal recessive caused by biallelic pathogenic variants of the SLC26A4 gene (solute carrier family 26, member 4)." (PMID 40225947, 2024). "More than 150 mutations have been identified in the SLC26A4 gene to be associated with Pendred syndrome characterized by enlargement of the thyroid gland, hearing loss, and other abnormalities of the inner ear, including an enlarged vestibular aqueduct." (PMID 39100210, 2024). "Enlarged Vestibular Aqueduct Syndrome (EVAS) is a congenital inner ear abnormality, with studies indicating an association with Pendred syndrome and mutations, primarily in the SLC26A4 (PDS) gene." (PMID 39481243, 2024). "Mutations in the SLC26A4 gene are associated with Pendred syndrome, an inherited disorder characterized by sensorineural hearing loss, goiter (enlargement of the thyroid gland), and sometimes inner ear abnormalities such as vestibular dysfunction." (PMID 39100210, 2024). "In Thailand, c.919-2A>G was found in one third of all mutated SLC26A4 alleles in a small sample of patients with Pendred syndrome." (PMID 37107686, 2023). "The homozygous or compound heterozygosity of pathogenic variants in SLC26A4 cause Pendred syndrome, which is described as including sensorineural hearing loss, developmental malformations of the inner ear, and thyroid dyshormonogenesis." (PMID 36614229, 2023). "SLC26A4 mutations are either responsible for autosomal recessive NSHL with enlarged vestibular aqueduct (OMIM #600791) or Pendred syndrome (OMIM #274600) accompanied by hypothyroid goiter and increased risk for thyroid cancer." (PMID 37108562, 2023). "SLC26A4 mutations are one of the most frequent causative factors of congenital HL, including Pendred syndrome and DFNB4, and the splicing mutation (c.919-2A > G) in intron 7 of SLC26A4 is a hotspot mutation among Asian populations." (PMID 37210555, 2023).
Pendred syndrome (continued). "It should be noted that autosomal recessive SNHL with EVA and/or Pendred syndrome also can be diagnosed with one pathogenic variant in SLC26A4 and one in either FOXI1 or KCNJ10." (PMID 36675424, 2023). "Genetic causes included autosomal recessive non-syndromic hearing loss (GJB2/connexin 26), Townes–Brocks syndrome (SALL1), Pendred syndrome (SLC26A4) and Chromosome 8P inverted duplication and deletion syndrome, and CHARGE syndrome (CHD7)." (PMID 36675424, 2023). "Pathogenic variants of SLC26A4 lead to the development of DFNB4 and Pendred syndrome, in which HL is accompanied by abnormal organification of iodine, which leads to development of goiter with or without hypothyroidism." (PMID 36833263, 2023). "In Pendred's syndrome, associated with mutations of the SLC26A4 gene, the incomplete partition type II constitutes a characterizing element of the malformative spectrum, together with the presence of an enlarged vestibular aqueduct and thyroid goiter." (PMID 36923273, 2023). "The causes were autosomal recessive non-syndromic hearing loss (GJB2), Townes–Brocks syndrome (SALL1), Pendred Syndrome (SLC26A4), Chromosome 8P inverted duplication and deletion syndrome, and CHARGE syndrome (CHD7)." (PMID 36675424, 2023). "Pendred syndrome is an autosomal recessive disorder characterized by bilateral sensorineural deafness and goitre caused by mutations in the SLC26A4 (PDS) gene (7q12–34)." (PMID 35255942, 2022). "This is also supported by the fact that thyroid function is normal in more than half of Pendred syndrome cases caused by SLC26A4 dysfunction, and that Slc26a4 knockout mice on a low iodine diet show normal thyroid hormone levels." (PMID 35788623, 2022). "We found that the reported SLC26A4 mutations were mainly located between positions 508–708, with clinical manifestations of Pendred syndrome or sensorineural hearing loss." (PMID 35249537, 2022). "The SLC26A4 gene, which encodes the anion exchanger pendrin, is involved in determining syndromic (Pendred syndrome) and non-syndromic (DFNB4) autosomal recessive hearing loss." (PMID 36233414, 2022). "Mutations in the SLC26A4 gene that codes for the anion exchanger protein pendrin cause Pendred Syndrome (PDS), the most common type of syndromic hereditary HL." (PMID 36291196, 2022). "Mutations of SLC26A4 cause Pendred syndrome (OMIM #274600) and nonsyndromic autosomal recessive deafness 4 (OMIM #600791)." (PMID 35761346, 2022). "Pendred syndrome (PDS) is an autosomal recessive disorder caused by mutations in the SLC26A4 gene and characterized by congenital sensorineural deafness and diffuse goiter with or without hypothyroidism." (PMID 36242759, 2022). "Pendred syndrome is characterized by autosomal recessive inheritance of mutations to the SLC26A4 gene, goiter, hearing loss, and enlargement of the vestibular aqueduct." (PMID 35185769, 2022). "This variant was previously detected in an individual diagnosed with Pendred syndrome and a monoallelic pathogenic SLC26A4 variant." (PMID 34410491, 2022). "Next, 85 pathogenic/likely pathogenic variants in SLC26A4 were identified as the underlying molecular etiology of 278 patients diagnosed as Pendred syndrome or simple HL with enlarged vestibular aqueduct, of which 26 variants had not been previously reported." (PMID 35982127, 2022). "A recent report proposed a digenic inheritance of DFNB4/Pendred syndrome caused by monoallelic mutations in SLC26A4 and EPHA2." (PMID 34562878, 2021). "The c.2168A>G (p.His723Arg, rs121908362) mutation, detected only in Altaian patients, was one of the first SLC26A4 mutations identified in patients with Pendred syndrome and EVA." (PMID 34943614, 2021). "It has been confirmed that mutations in solute carrier family 26 member 4 (SLC26A4) contribute to pendred syndrome." (PMID 31998553, 2020).
Pendred syndrome (continued). "Another case patient, R197, was found to have an SLC26A4 mutation, which is known as a pathogenic variant for Pendred syndrome, according to Human Gene Mutation Database (HGMD) and dbSNP (MAF = 0.0001)." (PMID 32233732, 2020). "Pendred syndrome (PDS) is an autosomal recessive disorder caused by mutations in the SLC26A4 gene characterized by sensorineural hearing loss." (PMID 32666542, 2020). "Mutations in SLC26A4 have been related to Pendred syndrome, leading to sensorineuronal hearing loss." (PMID 32477112, 2020). "Homozygous mutations in the nearby gene SLC26A4 disrupt anion exchange in the inner ear and the thyroid, causing the recessive Pendred syndrome (OMIM 274600)." (PMID 32295532, 2020). "Previous studies have shown that a single nucleotide mutation in an enhancer regulating SLC26A4 can cause decreased enhancer activity leading to repression of gene expression, which in turn is associated with Pendred syndrome." (PMID 32243438, 2020). "SLC26A4-related Pendred syndrome (PDS) is characterized by hearing loss, starting in late childhood or early adulthood, and goiter with hypothyroidism." (PMID 32295532, 2020). "Pendred syndrome is caused by mutations in SLC26A4 encoding Pendrin which acts as Cl−/HCO3− exchanger in the inner ear, thyroid and kidney." (PMID 30760291, 2019). "Pendred syndrome, as defined by an abnormal perchlorate discharge test result, is correlated with biallelic mutations of SLC26A4 (M2)." (PMID 31266487, 2019). "With regard to Pendred syndrome, we identified SLC26A4 variants in 32 probands with autosomal recessive inheritance or sporadic cases." (PMID 31427586, 2019). "Mutations in the SLC26A4 gene are associated with Pendred syndrome and autosomal recessive non-syndromic deafness (DFNB4)." (PMID 29739340, 2018). "Pendred syndrome (PS) is an autosomal recessive disorder due to mutations in the SLC26A4 gene (chr7q22." (PMID 30555519, 2018). "Mutations in the SLC26A4 gene (NM_000441) were found to be causative of two autosomal recessive disorders, Pendred syndrome (OMIM # 274600) and one of the forms of non-syndromic autosomal recessive hearing loss (DFNB4; #600791)." (PMID 29739340, 2018). "Pathogenic variants in pendrin encoded by SLC26A4 can cause both nonsyndromic (DFNB4) and syndromic deafness (Pendred syndrome; PDS)." (PMID 28273078, 2017). "Mutations in SLC26A4, which encodes pendrin, are responsible for hearing loss with an enlarged vestibular aqueduct and Pendred syndrome." (PMID 27109633, 2016). "Variants in one member of this gene family, specifically in SLC26A4, have been shown to cause a genetic disorder called Pendred syndrome, characterised by goitre and occasionally also hypothyroidism." (PMID 26261983, 2015). "Biallelic mutations in the gene SLC26A4 have been shown to cause Pendred syndrome, accounting for its autosomal recessive inheritance." (PMID 23965030, 2013). "It was proposed that digenic inheritance of mutations in both FOXI1 and SLC26A4 were involved in the genetic basis of Pendred syndrome, as mutations in FOX1 were shown to reduce the transcription of SLC26A4." (PMID 23965030, 2013). "Mutations in SLC26A4 (strong support) or IYD (strong support) cause Pendred syndrome (OMIM ID 274600) or iodotyrosine deiodinase deficiency, respectively (OMIM ID 274800)." (PMID 23950964, 2013). "The evidence that genetic factors in addition to mutations in the coding region of the SLC26A4 gene contribute to Pendred syndrome and non-syndromic EVA has originated from both mouse and human studies." (PMID 23965030, 2013). "Mutations in the SLC26A4 gene are associated with Pendred syndrome (PS, MIM 274600) and non-syndromic enlarged vestibular aqueduct (EVA, MIM 600791)." (PMID 23555729, 2013). "Patients with Pendred syndrome, however, had higher mutation detection rate in SLC26A4 gene, 90% in a French study." (PMID 19040761, 2008).
Pendred syndrome (continued). "In addition, 1 patient was diagnosed with Pendred syndrome (SLC26A4) and 9 variants of high interest were found in other NMTC candidate susceptibility genes." (PMID 38415346, 2024). "Mutation in the SLC26A4 gene responsible for pendrin production leads to the development of an interesting clinical entity known as Pendred syndrome, which is characterized by bilateral sensorineural hearing loss and the development of euthyroid or hypothyroid goiter." (PMID 38182855, 2024). "Genetic causes for the uSNHL were found in 28% of subjects (5/18) including CHARGE syndrome (CHD7), autosomal recessive non-syndromic hearing loss (GJB2), Townes–Brocks syndrome (SALL1), Pendred Syndrome (SLC26A4) and Chromosome 8P inverted duplication and deletion syndrome." (PMID 36675424, 2023). "Mutations in SLC26A4 may cause SNHL in DFNB4 and Pendred syndrome, and mutations in BSND can lead to DFNB73." (PMID 37289589, 2023). "Moreover, pathogenic variants in the SLC26A4 gene are associated with Pendred syndrome (PS, OMIM #274600), in which sensorineural HL is combined with thyroid dysfunction." (PMID 36499699, 2022). "In conclusion, Pendred syndrome patients with SLC26A4 mutation may have certain metabolic abnormalities." (PMID 36107570, 2022). "Pendred syndrome is associated with recessive variants in the SLC26A4 gene." (PMID 36529647, 2022). "Mutations in the SLC26A4 gene are involved in syndromic deafness featured on congenital sensorineural hearing impairment and goiter (Pendred syndrome, OMIM 274600) as well as in congenital isolated deafness (DFNB4; OMIM 600791), both of which are relevant to an enlarged vestibular aqueduct (EVA)." (PMID 35249537, 2022). "Here we identify EPHA2 as another causative gene of Pendred syndrome with SLC26A4." (PMID 32165640, 2020). "Although patients with Pendred syndrome carry biallelic loss-of-function mutations in the pendrin gene SLC26A4 and are characterised by congenital hypothyroidism and hearing loss, they can maintain normal thyroid hormone levels, as can Slc26a4 knockout mice." (PMID 31372509, 2019). "Recent studies applying molecular testing for SLC26A4 mutations and radiological imaging of temporal bones have demonstrated that enlargement of the vestibular aqueduct can be recognized as the most penetrant feature of Pendred syndrome." (PMID 31131597, 2019). "Pendred syndrome is caused by mutations of the gene SLC26A4, which codes for the protein pendrin." (PMID 17187680, 2006). "Detailed studies aimed at identifying the direct cause of deafness in Pendred syndrome have recently become possible due to the generation of a pendrin-specific polyclonal antibody and the development of Slc26a4-/- mice, which bear a targeted disruption of the mouse Slc26a4 gene." (PMID 15320950, 2004). "The present study investigates whether variants in KCNJ10 and FOXI1 in combination with heterozygosity for SLC26A4 mutations are likely to be associated with the disease phenotype seen in Pendred syndrome/EVA patients (who already have one mutation in the SLC26A4 gene)." (PMID 23965030, 2013). "Pendred syndrome and autosomal recessive non-syndromic hearing loss, type 4 (DFNB4), are associated with mutations in SLC26A4 that encodes the anion transporter SLC26A4 (pendrin)." (PMID 39932986, 2025). "Pathogenic SLC26A4 variants have been linked to non-syndromic deafness DFNB4 (MIM #600,791) and Pendred syndrome (PS, MIM #274,600), both of which involve an enlarged vestibular aqueduct and progressive/fluctuating sensorineural hearing impairment (SNHI)." (PMID 40507794, 2025). "iPSCs derived from Pendred syndrome patients with biallelic SLC26A4 point variations have provided new insights into how pendrin protein dysfunction leads to hearing loss." (PMID 41227304, 2025). "SLC26A4 is a well-known cause of inherited diseases, including autosomal recessive non-syndromic deafness, DFNB4, and Pendred syndrome." (PMID 38673775, 2024).